AUNIP (aurora kinase A and ninein interacting protein)
Description:
DNA-binding protein that accumulates at DNA double-strand breaks (DSBs) following DNA damage and promotes DNA resection and homologous recombination. Serves as a sensor of DNA damage: binds DNA with a strong preference for DNA substrates that mimic structures generated at stalled replication forks, and anchors RBBP8/CtIP to DSB sites to promote DNA end resection and ensuing homologous recombination repair. Inhibits non-homologous end joining (NHEJ). Required for the dynamic movement of AURKA at the centrosomes and spindle apparatus during the cell cycle.
Synonyms: AIBp; C1orf135; MGC2603
Tractability: PROTAC: ubiquitination databases record sites on it.
Gene: Protein-coding gene on chromosome 1 (25,831,913 to 25,859,458, reverse strand). Ensembl gene ENSG00000127423.
Subcellular location: Nucleus; Chromosome; Cytoplasm, cytoskeleton, microtubule organizing center, centrosome; Cytoplasm, cytoskeleton, spindle pole
Subcellular location (Human Protein Atlas): Centrosome
Gene Ontology:
Molecular function: damaged DNA binding; protein binding
Biological process: double-strand break repair via homologous recombination; negative regulation of double-strand break repair via nonhomologous end joining; spindle organization
Cellular component: centrosome; chromosome; nucleus; site of DNA damage; spindle pole
Genetic constraint (gnomAD): Loss-of-function variants: 21 observed, 17.69 expected, observed/expected ratio (o/e) 1.19, 90% interval 0.84 to 1.69. The upper end of that interval is the gene's LOEUF score, 1.69, which puts it in group 6 of 6, group 1 being the genes least tolerant of losing a copy. Missense variants: 411 observed, 429.18 expected, observed/expected ratio (o/e) 0.96, 90% interval 0.88 to 1.04. Synonymous variants: 142 observed, 156.59 expected, observed/expected ratio (o/e) 0.91, 90% interval 0.79 to 1.04.
Homologues: Orthologues: chimpanzee AUNIP (97% identical), macaque AUNIP (93% identical), dog AUNIP (68% identical), pig AUNIP (68% identical), rabbit AUNIP (66% identical), guinea pig AUNIP (63% identical), mouse Aunip (57% identical), rat Aunip (55% identical).
Diseases named in the same sentence as AUNIP in open-access papers:
AUNIP is named in the same sentence as 19 diseases in open-access papers, as found by Europe PMC text mining. Sharing a sentence is not in itself a finding about the gene and the disease. The quoted sentences say what the papers report.
oral squamous cell carcinoma (4 papers, 2020 to 2025). "AUNIP expression is associated with the tumor microenvironment and immune infiltration in oral squamous cell carcinoma, hepatocellular carcinoma, and lung adenocarcinoma." (PMID 35846349, 2022). "AUNIP, a novel prognostic biomarker, has been shown to be associated with stromal and immune scores in oral squamous cell carcinoma (OSCC)." (PMID 33363020, 2020). "The research identified AUNIP, a gene, as a potential biomarker for the diagnosis and prognosis of oral squamous cell carcinoma (OSCC)." (PMID 39941210, 2025). "Furthermore, recent research has found that AUNIP regulates the cell cycle of oral squamous cell carcinoma (OSCC) cells and can be used as a prognostic biomarker for OSCC." (PMID 33363020, 2020).
mesothelioma (3 papers, 2020 to 2025). A usually malignant and aggressive neoplasm of the mesothelium which is often associated with exposure to asbestos. "AUNIP expression was associated with OS in 10 diverse types of cancers, namely, LIHC, LUAD, PAAD, UCEC, KIRC, KIRP, sarcoma (SARC), adrenocortical carcinoma (ACC), brain lower grade glioma (LGG), and mesothelioma (MESO)." (PMID 33363020, 2020). "A Kaplan-Meier survival analysis revealed that high expressions of AUNIP, FANCI, LASP1, PSMD8, and XPO5 were clearly associated with poor OS and RFS, suggesting that the five candidate genes play important roles in the tumorigenesis and progression of mesothelioma." (PMID 35846349, 2022). "AUNIP overexpression had adverse outcomes in adrenocortical carcinoma (ACC), brain lower grade glioma (LGG), LIHC, mesothelioma (MESO), and sarcoma (SARC)." (PMID 40386627, 2025). "AUNIP, FANCI, LASP1, PSMD8, and XPO5 are putative antigens for the development of anti-mesothelioma mRNA vaccine and patients with the IS1 subtype may be considered for vaccination." (PMID 35846349, 2022).
astrocytoma (1 paper, 2025). "AUNIP is highly expressed in astrocytoma and other brain tumors, suggesting that AUNIP may play a role as oncogenic genes in the development of brain tumors." (PMID 40386627, 2025).
human papillomavirus infection (1 paper, 2021). "It was demonstrated that AUNIP was associated with TME, human papillomavirus infection, and cell cycle in OSCC." (PMID 35003322, 2021).
paraganglioma (1 paper, 2020). A benign or malignant neoplasm arising from paraganglia located along the sympathetic or parasympathetic nerves. "However, AUNIP expression in pheochromocytoma and paraganglioma (PCPG), kidney renal papillary cell carcinoma (KIRP), and kidney renal clear cell carcinoma (KIRC) significantly decreased relative to that in corresponding non-carcinoma tissues." (PMID 33363020, 2020).
prostate adenocarcinoma (1 paper, 2020). "Furthermore, AUNIP expression was markedly correlated with the infiltration degrees of at least four immunocyte types in each of four cancer types, comprising KIRC, STAD, prostate adenocarcinoma (PRAD), and thymoma (THYM)." (PMID 33363020, 2020).
tumor (5 papers, 2020 to 2025). "In conclusion, AUNIP, which is associated with tumor immune infiltration, is a candidate diagnostic and prognostic biomarker for HCC and LUAD." (PMID 33363020, 2020). "The Tumor Immune Estimation Resource (TIMER) tool was utilized to determine the potential associations of AUNIP expression with tumor-infiltrating immunocytes." (PMID 33363020, 2020). "AUNIP was negatively associated with 30 small-molecule drugs that inhibit tumor development." (PMID 40386627, 2025). "A total of five potential tumor antigens correlated with prognosis and infiltration of antigen-presenting cells, including AUNIP, FANCI, LASP1, PSMD8, and XPO5 were identified." (PMID 35846349, 2022). "In this study, we identified five tumor antigens (AUNIP, FANCI, LASP1, PSMD8, and XPO5) that were considered promising candidates as mRNA-based vaccines." (PMID 35846349, 2022). "Lastly, the Tumor Immune Estimation Resource (TIMER) tool was used to determine the correlations of AUNIP expression with tumor immune infiltration." (PMID 33363020, 2020). "In general, the relationships of AUNIP expression with immune cell markers revealed that AUNIP was involved in regulating tumor immunity in HCC and LUAD." (PMID 33363020, 2020). "AUNIP expression was significantly related to tumor purity in 13 cancer types and to the B cell infiltration degree in 14 cancer types." (PMID 33363020, 2020). "Finally, we demonstrated the differential expression of the key nucleotide metabolism gene AUNIP acts as an oncogene to promote LUAD cell proliferation and is associated with tumor immune infiltration." (PMID 39148731, 2024). "Therefore, immunotherapy using mRNA vaccines targeting previously recognized tumor antigens (AUNIP, FANCI, LASP1, PSMD8, and XPO5) could induce immune cell infiltration to reinvigorate the ISI patient’s immune system." (PMID 35846349, 2022). "Furthermore, AUNIP expression is related to the tumor infiltration degrees of various immune cells." (PMID 33363020, 2020). "We found that AUNIP was negatively related to IC50 values of 30 drugs, indicating that these drugs stop the progression of the tumor." (PMID 40386627, 2025). "Later, we discovered that the expression of AUNIP in LUAD tumor tissue was higher than in the adjacent non-cancerous tissue." (PMID 39148731, 2024). "AUNIP, FANCI, LASP1, PSMD8, and XPO5 are putative tumor antigens for mRNA vaccine development." (PMID 35846349, 2022). "As a result, AUNIP expression was found to be significantly correlated with 20 and 7 markers in HCC and LUAD, respectively, and 21 and 7 markers, respectively, after correction for tumor purity." (PMID 33363020, 2020).
cancer (4 papers, 2020 to 2025). A tumor composed of atypical neoplastic, often pleomorphic cells that invade other tissues. "AUNIP was associated with T stage, N stage, and clinicopathological analysis in several cancers and AUNIP expression had a correlation with histologic grade in LIHC by IHC." (PMID 40386627, 2025). "Next, RNA-seq and survival data from the TCGA database were used to investigate whether AUNIP expression was associated with OS in a pan-cancer analysis." (PMID 33363020, 2020). "The association of AUNIP with Aurora-A might underlie the relationship between AUNIP expression and poor cancer prognosis." (PMID 33363020, 2020). "Furthermore, AUNIP expression was related to the T stage, N stage, and clinicopathological stage in some cancers, indicating that AUNIP may be a promising valuable diagnostic and prognostic marker in multiple tumors." (PMID 40386627, 2025). "GSEA results suggested that AUNIP mainly participated in the cell cycle, DNA replication, mismatch repair, and homologous recombination.Pan-cancer study considered AUNIP as a potential prognostic marker and high latent diagnostic biomarker." (PMID 40386627, 2025). "In our work, the expression, prognosis, and characteristics of AUNIP were elucidated by pan-cancer analysis." (PMID 40386627, 2025). "Among the remaining immune cells, AUNIP had a correlation with one or more immune cells in different cancers." (PMID 40386627, 2025). "Several potential mechanisms regarding the relationship between high AUNIP expression and poor cancer prognosis have been proposed in recent studies." (PMID 33363020, 2020). "We also evaluated the correlations between AUNIP expression and immune infiltration in other cancer types." (PMID 33363020, 2020). "An analysis of 11 HCC cohorts in the HCCDB database showed that AUNIP mRNA expression remarkably increased in HCC relative to adjacent non-carcinoma tissues in 10 HCC cohorts, with the difference being non-significant in the remaining HCC cohort." (PMID 33363020, 2020). "It was found that AUNIP expression was increased significantly in most tumors compared to normal tissues, suggesting that AUNIP may be a key gene in cancer development." (PMID 40386627, 2025). "We detected changes in AUNIP mRNA expression based on a pan-cancer analysis." (PMID 33363020, 2020). "In addition, AUNIP was related to the immune infiltration degrees in additional cancer types, including KIRC, PRAD, STAD, and THYM." (PMID 33363020, 2020). "TCGA data were utilized to analyze the AUNIP mRNA expression in diverse cancer types." (PMID 33363020, 2020). "However, AUNIP was down-regulated in other cancer types, comprising KIRC, KIRP, and PCPG, which might be due to differences in the underlying pathogenic mechanisms involved in these cancers." (PMID 33363020, 2020). "The expression of AUNIP escalated with the severity of OSCC, and its inhibition curtailed cancer cell proliferation." (PMID 39941210, 2025). "However, the role and mechanism of AUNIP in other types of cancer remain unclear." (PMID 33363020, 2020). "AUNIP is a potential diagnostic and prognostic biomarker in OSCC, but its significance as a diagnostic and prognostic biomarker in other cancers has not previously been evaluated." (PMID 33363020, 2020). "In addition, AUNIP expression was significantly related to the infiltration degree of CD4+ T cells, CD8+ T cells, neutrophils, macrophages, and DCs in 11, 12, 15, 14, and 15 cancer types, respectively." (PMID 33363020, 2020). "However, the roles of AUNIP and CILP in this malignant tumor have not been fully studied." (PMID 41585903, 2025).
AUNIP also shares sentences with these, for which no sentence is quoted: hepatocellular carcinoma (3 papers); lung adenocarcinoma (3); sarcoma (2); adrenocortical carcinoma (1); brain tumors (1); Fanconi anemia (1); liver cancer (1); lung carcinoma (1); pancreatic cancer (1); pheochromocytoma (1); thymoma (1).